SCGB1A1 (secretoglobin family 1A member 1)
Description:
Binds phosphatidylcholine, phosphatidylinositol, polychlorinated biphenyls (PCB) and weakly progesterone, potent inhibitor of phospholipase A2.
Synonyms: CCPBP; CC10; UP-1; UP1; CCSP; UGB; CC16
Tractability: Antibody: UniProt places it where antibodies can reach, with medium confidence; UniProt predicts a signal peptide or a membrane-spanning region; its Gene Ontology location is reachable by antibodies, with medium confidence.
Gene: Protein-coding gene on chromosome 11 (62,405,103 to 62,423,195, forward strand). Ensembl gene ENSG00000149021.
Subcellular location: Secreted
Gene Ontology:
Molecular function: protein binding; polychlorinated biphenyl binding
Biological process: embryo implantation; female pregnancy; signal transduction; response to cytokine; response to fibroblast growth factor; response to glucocorticoid; response to lipopolysaccharide; response to ozone; response to silicon dioxide; response to xenobiotic stimulus
Cellular component: extracellular exosome; extracellular region; cytoplasm; nuclear envelope; secretory granule
Genetic constraint (gnomAD): Loss-of-function variants: 9 observed, 8.46 expected, observed/expected ratio (o/e) 1.06, 90% interval 0.64 to 1.75. That is too few expected variants to judge how well the gene tolerates losing a copy. Missense variants: 121 observed, 113.25 expected, observed/expected ratio (o/e) 1.07, 90% interval 0.92 to 1.24. Synonymous variants: 44 observed, 41.61 expected, observed/expected ratio (o/e) 1.06, 90% interval 0.83 to 1.36.
Homologues: Orthologues: chimpanzee SCGB1A1 (99% identical), macaque SCGB1A1 (81% identical), pig SCGB1A1 (57% identical), mouse Scgb1a1 (55% identical), rat Scgb1a1 (55% identical). Paralogues in human: SCGB1C1 (29% identical), SCGB1C2 (29% identical).
Diseases named in the same sentence as SCGB1A1 in open-access papers:
SCGB1A1 is named in the same sentence as 95 diseases in open-access papers, as found by Europe PMC text mining. Sharing a sentence is not in itself a finding about the gene and the disease. The quoted sentences say what the papers report.
asthma (37 papers, 2010 to 2026). "If, as proposed, asthma is an IgE-associated bronchospastic disease attributable to acarian species, and SCGB1A1 has an anti-acarian role, then one would expect both low levels and mutations of SCGB1A1 to influence the development of the disease." (PMID 39552700, 2024). "Decreased expression of Scgb1a1 is associated with multiple lung diseases such as emphysema, chronic obstructive pulmonary disease (COPD), and asthma and has become an important therapeutic target for chronic lung inflammation." (PMID 41822759, 2026). "Given global HK2 deletion is embryonically lethal, we generate Hk2 flox/flox Scgb1a1-iCre+/- mice to explore how HK2 functions in asthma." (PMID 40643524, 2025). "To further investigate the function of HK2 in asthma, we generated Hk2flox/flox-Scgb1a1-iCre+/- mice, in which HK2 was specifically deleted in club cells." (PMID 40643524, 2025). "Serum SCGB1A1 levels were found to be lower in patients with asthma and allergic rhinitis compared to healthy controls." (PMID 38892470, 2024). "SCGB1A1 is especially abundant in the peripheral airways and patients with asthma, COPD, and obliterative bronchiolitis after lung transplantation have deficient SCGB1A1 expression in their airways." (PMID 36193088, 2022). "In contrast to the decrease of club cell numbers in COPD and asthma, SCGB1A1, the major secretory product of club cells, is increased in both serum and bronchoalveolar lavage (BAL) fluid of IPF patients." (PMID 32941426, 2020). "SCGB1A1 is considered a key molecule for homeostasis in the lung, and club cells and SCGB1A1 are reduced in horses with severe asthma." (PMID 28886691, 2017). "Asthma relevant proteins that were shown to be different in asthmatics vs controls included SCGB1A1, SERPINA1, thrombins and fibrinogens." (PMID 21939520, 2011). "Moreover, Secretoglobin, Family 1A, Member 1 (SCGB1A1), which is often used as a gene expression marker of Club cell, was negatively downregulated in severe asthma compared to health in both central airways and in peripheral airways." (PMID 28045928, 2017). "It was previously reported that horses with recurrent airway obstruction (RAO), an asthma-like chronic inflammatory condition affecting mature individuals, have ultrastructural changes in Clara cells, decreased lung SCGB1A1 gene expression and reduced BAL fluid SCGB 1A1 concentration." (PMID 23253434, 2012). "However, B-cell lymphoma 2 (BCL2) expression was lower, and SCGB1A1 was higher in asthmatics compared to control, which contrasts with results in severe asthma in horses and may be due to different experimental design and different phases of disease being assessed." (PMID 28886691, 2017). "Gene specific assessment of transcripts showed approximately 2.5 fold higher expression of SCGB1A1A than SCGB1A1 in lung and uterus of control animals, and an increased ratio in lung tissue of animals with RAO, an asthma-like condition." (PMID 23253434, 2012). "Scgb1a1-CreTg mice developed signs of asthma pathology that were indistinguishable from their Scgb1a1-CreWT littermates, as judged by histopathological analysis, BALF inflammatory cell quantitation, TH2 cytokine secretion by MLN cells and serum IgE production." (PMID 34045680, 2021).
lung carcinoma (21 papers, 2009 to 2025). "The expression of SCGB1A1 also appears to be inversely correlated to regression of bronchial dysplasia and improvement in sputum cytometry assessment in smokers withhigh lung cancer risk." (PMID 27081700, 2016). "Previous reports demonstrated that SCGB1A1 is a tumor suppressor that is downregulated in human lung cancer." (PMID 36467500, 2022). "IL10-deficient Kras4bG12D- and EGFRL858R-induced lung cancer mice (Scgb1a1-rtTA/TetO-Kras4bG12D/IL10−/− and Scgb1a1-rtTA/TetO-EGFRL858R/IL10−/−) were established for this purpose." (PMID 26956044, 2016). "In addition, it also has been reported that SCGB1A1+ club cells could increase the efficacy of ICB in lung cancer by promoting infiltration of cytotoxic cells." (PMID 36869384, 2023). "After optimization and quality control of the methylome deconvolution model (for details, see “Methods”), we identified three main LMCs: LMC1 and LMC3 represented normal samples from Scgb1a1 and Sftpc lineages, respectively, whereas LMC2 represented a common lung cancer-specific signature." (PMID 35931677, 2022).
lung diseases (19 papers, 2005 to 2026). "Previous studies showed that SCGB1A1 was reduced in horses with RAO compared to those without lung disease, but did not assess expression of individual genes." (PMID 24777050, 2014).
pulmonary fibrosis (19 papers, 2012 to 2025). Chronic progressive interstitial lung disorder characterized by the replacement of the lung tissue by connective tissue, leading to progressive dyspnea, respiratory failure, or right heart failure. "We postulate that pulmonary fibrosis and SCGB1A1+ club cell-rich areas of alveolar bronchiolization represent potential risk factors for other diseases in long-COVID survivors." (PMID 40021627, 2025). "In contrast, SCGB1A1 expression is increased in both serum and epithelial lining fluid of idiopathic pulmonary fibrosis (IPF)." (PMID 32941426, 2020). "SCGB1A1, the founding member of the SCGB gene superfamily was reported to possess anti-fibrotic activity when Scgb1a1-null mice were subjected to the BLM-induced pulmonary fibrosis model." (PMID 26559674, 2015). "During the chronic phase of the disease, we observed mild to moderate but persistent pathomorphological changes like sub-pleural and interstitial pulmonary fibrosis as well as alveolar bronchiolization areas dominated by SCGB1A1+ club cells and fewer CK14+ basal cells." (PMID 40021627, 2025). "There results suggest that the lack of SCGB3A2 expression, but not those of surfactant proteins and SCGB1A1 is likely to result in increased susceptibility of Sgb3a2-null mice to BLM-induced pulmonary fibrosis." (PMID 26559674, 2015). "Importantly, surfactant proteins and SCGB1A1 appear not to be involved in the susceptibility of Scgb3a2-null mice to BLM-induced pulmonary fibrosis." (PMID 26559674, 2015). "It was recently demonstrated that antiflammin-1, the carboxyl-terminal part of the third α-helix of SCGB1A1, has anti-inflammatory and anti-fibrotic activities in BLM-induced pulmonary fibrosis model." (PMID 26559674, 2015). "Interestingly, statistically significant non-parametric correlations were found between SCGB1A1/EH and two surrogate markers of lung fibrosis." (PMID 33717159, 2021). "Similar conclusions were reached using the Secretoglobin Family 1A Member 1 (Scgb1a1)-CreER driver, which labeled clara cells as well as a few scgb1a1 and sftpc dual positive cells and concluded that epithelial cells were not the source of myofibroblasts in bleomycin-induced pulmonary fibrosis." (PMID 36769178, 2023). "In contrast, a recent study using mouse genetic tools to track the fates of lung epithelial cells showed that both alveolar type II cells and Scgb1a1-positive lung cells are not a major source of myofibroblasts through EMT, suggesting that EMT does not directly contribute to lung fibrosis in vivo." (PMID 24063588, 2013).
lung adenocarcinoma (17 papers, 2008 to 2025). A carcinoma that arises from the lung and is characterized by the presence of malignant glandular epithelial cells. "It is derived from an orthotopic Scgb1a1-CreERT; KP mouse model, ensuring its origin from lung epithelial cells, which accurately reflects human lung adenocarcinoma." (PMID 39358651, 2024). "#016225) to generate a conditional lung adenocarcinoma model (Scgb1a1-CreERT;KP mice)." (PMID 38853999, 2024). "It has been suggested that lung adenocarcinoma may arise from Scgb1a1, Sftpc dual positive putative bronchial alveolar stem cells (BASCs), that reside near the BADJ." (PMID 20548776, 2010).
chronic obstructive pulmonary disease (12 papers, 2010 to 2026). A chronic and progressive lung disorder characterized by the loss of elasticity of the bronchial tree and the air sacs, destruction of the air sacs wall, thickening of the bronchial wall, and mucous accumulation in the bronchial tree. "Reduced serum, sputum, and bronchoalveolar lavage fluid SCGB1A1 levels have been associated with increased tobacco smoke induced chronic obstructive pulmonary disease (TS-COPD) severity and accelerated lung function decline." (PMID 34564359, 2021). "Decreased serum levels of SCGB1A1 have been associated with tobacco smoke induced chronic obstructive pulmonary disease (TS-COPD)." (PMID 34564359, 2021). "There is clear evidence for tobacco use to cause its repression, and in a cross-sectional study, decreased SCGB1A1 serum levels were associated with tobacco smoke induced chronic obstructive pulmonary disease while smoking cessation for 3, 6 and 9 months restored SCGB1A1 level in BAL fluid." (PMID 37932771, 2023).
COVID-19 (11 papers, 2020 to 2025). A disease caused by infection with severe acute respiratory syndrome coronavirus 2. "The early loss of Scgb1a1 and surfactant protein genes is consistent with reported human COVID-19 autopsy data." (PMID 35857635, 2022). "In terms of addressing PASC prevalence being higher in human female COVID-19 cases, we did identify disruption in the lung-relevant SCGB1A1 at 31 dpi which was not changed in males." (PMID 40295670, 2024). "The Cox regression analyses suggested that 9 prognostic genes (ANPEP, OAS1, SCGB1A1, HLA‐A, NPPB, FGB, CCL2, TLR4, and SERPINE1) might act critical roles in the treatment of UCEC/COVID-19." (PMID 36969077, 2023). "Then, regression analyses indicated that 9 prognostic genes (including ANPEP, OAS1, SCGB1A1, HLA‐A, NPPB, FGB, CCL2, TLR4, and SERPINE1) might play important roles in quercetin for treating UCEC/COVID-19." (PMID 36969077, 2023).
emphysema (7 papers, 2013 to 2026). "In addition, the COPDGene study evaluated a combination of bio-markers and important health outcomes in COPD and observed that SCGB1A1 was associated with emphysema progression, airflow limitation, and mortality." (PMID 34564359, 2021).
influenza (7 papers, 2012 to 2024). An acute viral infection of the respiratory tract, occurring in isolated cases, in epidemics, or in pandemics; it is caused by serologically different strains of viruses (influenzaviruses) designated A, B, and C, has a 3-day incubation period, and usually lasts for 3 to 10 days. "Studies have shown that the lung secretoglobin, secretoglobin family 1A member 1 (Scgb1a1), plays a protective role in the immune response to influenza infection by decreasing the proinflammatory immune responses." (PMID 38163670, 2024). "scRNA-seq analysis at 28 days after influenza infection shows that Sox2 lineage-traced cells can generate bona fide AT2 cells, as indicated by expression of canonical AT2 markers such as Sftpc and Lamp3, but with very low levels of secretory cell markers such as Scgb1a1." (PMID 38182591, 2024).
viral infection (7 papers, 2015 to 2026). "Thus, we show for the first time that club cells producing SCGB1A1 not only can produce mucus after virus infection but also produce increased amounts of BPIFA1." (PMID 25531566, 2015). "However, the modulation of SCGB1A1 and BPIFA1 expression does suggest a role for these factors during the viral infection." (PMID 25531566, 2015). "On the other hand in SCGB1A1-hACE2 mice, the innate immune cells including F4/80 positive macrophages alone could not contain the level of virus infection at 2dpi, which led the increased number of PTPRC and CD3 positive adaptive immune cells at 5, 7dpi." (PMID 36457995, 2022).
allergic disease (4 papers, 2010 to 2024). An immune response that occurs following re-exposure to an innocuous antigen, and that requires the presence of existing antibodies against that antigen. "SCGB1A1 is involved in the pathophysiology of allergic diseases." (PMID 38892470, 2024).
bronchopulmonary dysplasia (4 papers, 2012 to 2021). Bronchopulmonary dysplasia is a chronic respiratory disease that results from complications related to lung injury during the treatment of infant acute respiratory distress syndrome in low-birth-weight premature infants or from abnormal lung development in older infants. "SCGB1A1 levels was sharply reduced in the bronchoalveolar lavage fluid of neonates that developed bronchopulmonary dysplasia, a risk factor for developing COPD later in life." (PMID 34564359, 2021).
interstitial lung disease (4 papers, 2020 to 2025). A diverse group of lung diseases that affect the lung parenchyma. "As there are very few data on their relationship with exposure to respiratory hazards and interstitial lung diseases, this review will focus only on the club cell secretory protein (CCSP), which is an accepted name for the SCGB1A1 gene product." (PMID 38255185, 2023).
ovarian carcinoma (3 papers, 2022 to 2024). A malignant neoplasm originating from the surface ovarian epithelium. "Furthermore, SCGB1A1 was considered as a biomarker for ovarian cancers with poor outcomes." (PMID 36969077, 2023).
schizophrenia (3 papers, 2016 to 2022). A major psychotic disorder characterized by abnormalities in the perception or expression of reality. "Low SCGB1A1 concentrations have previously been observed in serum of patients with depression, in response to stress in patients with stress-induced anxiety, and in plasma of patients with schizophrenia." (PMID 35697758, 2022).
bacterial pneumonia (2 papers, 2023). Acute infection of the lung parenchyma caused by bacteria (e.g., Streptococcus pneumoniae, Haemophilus influenzae, Chlamydia pneumoniae, Mycoplasma pneumoniae, and Legionella pneumophila). "Inhibition of ABL1 activity promotes lung regeneration through expansion of an SCGB1A1 + SPC + cell population following bacterial pneumonia." (PMID 37280583, 2023). "Furthermore, ablation of ABL1 (Abelson kinase-1) in SCGB1A1-expressing secretory cells promotes the expansion of a small SCGB1A1/SPC (surfactant protein C) double positive population to replenish distal ATI cells that are injured during bacterial pneumonia." (PMID 36829255, 2023).
breast carcinoma (2 papers, 2010 to 2020). "CK-5 and P63 were picked because they are both markers of squamous cell carcinoma, and SFTPC, SCGB1A1, and HOPX are markers of LUAD, while CDH1 was picked because SLFN12 has been demonstrated to modulate CDH1 expression in prostate and breast cancers." (PMID 32987632, 2020). "To begin to elucidate the mechanism of Sox2-induced neoplasia, we stained sections of tumors from Scgb1a1-CreER; homozygous Rosa26R-Sox2-IRES-GFP lungs for Cyclin D1, a target of Sox2 in breast cancer cell lines." (PMID 20548776, 2010).
bronchiectasis (2 papers, 2020 to 2021). Segmental, irreversible dilation of the bronchial tree resulting in the accumulation of secretions which leads to obstruction. "Low densities of SCGB1A1-marked cells correlate with bronchiectasis and fibrotic changes." (PMID 33717159, 2021).
chronic rhinosinusitis (2 papers, 2011 to 2021). Chronic form of sinusitis. "The aim of this study was to investigate the expression regulation of SCGBs other than SCGB1A1 (CC10) in human upper airway, and their potential involvement, particularly that of SCGB3A2 (UGRP1), in chronic rhinosinusitis (CRS) with nasal polyps (CRSwNP) and without nasal polyps (CRSsNP)." (PMID 21385388, 2011).
lung adenoma (2 papers, 2014 to 2025). A benign, well circumscribed epithelial neoplasm that arises from the bronchus or the lung parenchyma. "The differentially expressed genes in CPAM samples are mainly related to genes associated with airway epithelial cells, such as SCGB1A1, SCGB3A2, AGR3, and increased expression levels of these genes may be associated with proliferation and differentiation of lung adenoma cells." (PMID 40529122, 2025).
Adenovirus infection (1 paper, 2020). "The pro-inflammatory cytokine concentration and BAL cell count were significantly higher in Scgb1a1-deficient lungs following an acute Adenovirus infection." (PMID 33117399, 2020).
anorexia nervosa (1 paper, 2020). A disorder most often seen in adolescent females characterized by a refusal to maintain a minimally normal body weight, an intense fear of gaining weight, a disturbance in body image, and, in postmenarcheal females, the development of amenorrhea. "Across the four anorexia nervosa associated gene sets, four genes overlap between the Lutter damaging variants and Negraes iPSC derived gene set (TNFRSF10A, SCGB1A1, IFIT3, and GIPC3; hypergeometric test, p < 0.02)." (PMID 32651428, 2020).
aspergillosis (1 paper, 2021). Aspergillosis is an infection, growth, or allergic response caused by the Aspergillus fungus. "In this well-characterized model, Scgb1a1 is expressed by Club cell progenitor-derived small airway bronchiolar cells, a cell type responsible for viral-inducible remodeling and inflammation and sensitization to Aspergillosis." (PMID 34930252, 2021).
autoimmune disease (1 paper, 2020). A disorder resulting from loss of function or tissue destruction of an organ or multiple organs, arising from humoral or cellular immune responses of the individual to their own tissue constituents. "Given the high density of AMs in lung tissue, exogenous supplementation of SCGB1A1 may be helpful to restore AM SteadyState functions and prevent local cytokine surges in infectious and autoimmune diseases." (PMID 33117399, 2020).